SNORD70 (small nucleolar RNA, C/D box 70)
Synonyms: HBII-234; SNORD70A
Gene: Small nucleolar RNA gene on chromosome 2 (202,276,431 to 202,276,518, forward strand). Ensembl gene ENSG00000212534.
Gene Ontology:
Biological process: RNA processing
Cellular component: nucleolus
Homologues: Orthologues: macaque SNORD70 (98% identical), guinea pig SNORD70 (91% identical), rabbit SNORD70 (90% identical), mouse Snord70 (89% identical), rat Snord70 (88% identical), mouse Gm54847 (58% identical). Paralogues in human: SNORD70B (88% identical).